INS (insulin)
Diseases named in the same sentence as INS in open-access papers (continued):
Sharing a sentence is not in itself a finding about the gene and the disease.
Hyperglycemia (continued). "This cycle ultimately exhaust the pancreas, leading to β-cell failure and decompensation, resulting in the inability of the pancreas to produce/secrete sufficient amount of insulin needed, leading to hyperglycemia." (PMID 39070783, 2024). "In contrast, a chronic induction with the HFD-feeding seems to exert more consistent damage that results in a homogenous hyperglycemia probably as a consequence of the systemic insulin resistance (also corroborated by our experiments)." (PMID 38673735, 2024). "Three participants experienced mild to moderate hypoglycemia during the event; all experienced hyperglycemia 3 h post-exercise; ↓ insulin administration pre-race and 40–60 g/h of CHOs ↓ the occurrence of hypoglycemia and avoided hyperglycemia during the race." (PMID 39599728, 2024). "Minimising hyperglycaemia prior to, during and following surgical procedures can reduce treatment complications and improve outcomes; insulin use often plays a key role in achieving this objective." (PMID 39666732, 2024). "Chronic hyperglycemia and disease progression lead to a dysfunctional secretion of the β-cells, lowering insulin secretion in both phases." (PMID 39768947, 2024). "The secondary objectives included adverse events, hyperglycemia fluctuations, insulin dose requirements, and body weight changes." (PMID 39273299, 2024). "- Blood glucose >300 mg/dL, HbA1c >10%, symptoms of hyperglycemia, or evidence of catabolism.- Patients on treatment with 3 non-insulin therapies and insufficient control." (PMID 38559691, 2024). "It has been shown in mouse models that homozygous deletion of this gene leads to pancreatic agenesis, while heterozygous mutations, such as in patients with PDX1/IPF1 MODY, lead to impaired insulin production and hyperglycemia." (PMID 39408828, 2024). "Hyperglycemia develops when the release of insulin from the pancreas, which converts glucose to glycogen, is impaired, most of the time due to the damage and loss of pancreatic islet β cells as well insulin resistance." (PMID 39795285, 2024). "Corticosteroids have also been shown to impair the insulin secretion capacity of pancreatic beta-cells, which further exacerbates hyperglycemia." (PMID 38510914, 2024). "Impaired glucose resistance inhibits insulin release, resulting in impaired glucose uptake, hyperglycemia, and, ultimately, DM." (PMID 39493064, 2024). "When taken before meals and combined with preprandial insulin, it lowers postprandial hyperglycemia by decreasing postprandial hyperglucagonemia and delaying gastric emptying." (PMID 38338796, 2024). "Cisplatin is the most commonly used chemotherapeutic agent in CCRT and has been found to induce glucose intolerance through hyperglucagonemia and impaired insulin response to hyperglycemia." (PMID 38392055, 2024). "Previous studies employed pancreatic clamp techniques, where combinations of insulin, glucose, or somatostatin are administered to control for hyperglycemia or isolate the role of glucagon in hepatic glucose production." (PMID 38814331, 2024). "This aspect of stage 3 type 1 diabetes (i.e. when to start insulin once hyperglycaemia is confirmed) requires further evidence to support clinical practice, to better understand the metabolic and mental-health outcomes." (PMID 38910151, 2024). "Severe hyperglycemia can lead to glucotoxicity and pancreatic shock and prevent insulin secretion, resulting in underestimation of C-peptide level." (PMID 39108603, 2024). "T2D is characterized by fasting and post-prandial hyperglycemia resulting from inadequate insulin action." (PMID 39202758, 2024). "Using a previously established mouse model of GDM19,20, we show that lean GDM driven by impaired insulin secretion is characterized by a transient hyperglycaemia during pregnancy which reappeared after the lactation period." (PMID 38918525, 2024).
Hyperglycemia (continued). "As with our patient, temporary insulin therapy led to hyperglycemia resolution in all three patients within a short time, and notably, two of the patients had a greater than 5% increase in hemoglobin A1c, similar to our patient." (PMID 39105031, 2024). "TNF-α promotes carbohydrate dysregulation (hyperglycemia) by inhibiting insulin action, reducing glucose clearance (primarily by muscle and adipose tissue), and increasing hepatic glucose production." (PMID 39204094, 2024). "In our study, CUR and CUR NPs reduce hyperglycemia and ameliorate insulin sensitivity by increasing GLUT4." (PMID 39759349, 2024). "In response to hyperglycemia, beta cells of the pancreas synthesize and secrete the hormone insulin to lower serum glucose levels." (PMID 39594662, 2024). "The results indicated that treatment with either the glucagon receptor mAb or GABA alone mitigated hyperglycemia and increased insulin levels by regenerating beta cells." (PMID 39594662, 2024). "Optogenetic inhibition of the SF‐1‐expressing neurons impairs the recovery from insulin‐induced hypoglycemia, whereas optogenetic activation of those neurons increases blood glucose and induces profound hyperglycemia." (PMID 38751366, 2024). "This group also showed significant improvements in postprandial hyperglycemia and insulin sensitivity indices." (PMID 38347961, 2024). "Clock knockout mice show decreased proliferation and insulin secretion in pancreatic islets and hyperglycemia." (PMID 39165284, 2024). "The findings demonstrated that the continuous, combined consumption of GC and CGA for three weeks suppressed hyperglycemia and insulin levels after consuming a high-fat test meal and improved insulin sensitivity in healthy males." (PMID 38921480, 2024). "AAV-Hnf1α-mediated gene therapy prevented the development of hyperglycemia, hyperinsulinemia, increased glucose tolerance, and enhanced insulin secretion by the pancreatic islet apparatus, thereby reversing MODY3 in rodents." (PMID 39902162, 2024). "It is well recognized that hyperinsulinemia results from resistance to insulin in glucose metabolism, leading to increased blood glucose levels, which stimulates pancreatic β-cells to release insulin to avoid severe hyperglycemia." (PMID 38921456, 2024). "Insulin signaling has an important role in the regulation of blood glucose, and patients with IR are often accompanied by hyperglycemia." (PMID 38962445, 2024). "In cases of mild hyperglycemia, metformin can help improve the insulin peripheral effect while reducing hepatic glucose production." (PMID 38792534, 2024). "In this phase of type 1 diabetes, insulin therapy plus nutritional support is crucial for driving the patient from ketoacidosis and hyperglycemia to euglycemia and, thus, preserving residual β-cells’ endogen function." (PMID 39519472, 2024). "DM, which is one of the most common metabolic disorders in the world, is characterized by hyperglycemia due to decreased insulin secretion or insulin resistance." (PMID 38997451, 2024). "As expected, insulin treatment fully rescued the pronounced hyperglycemia and the majority of the GLUT alterations found in the lung of type 1 diabetic mice." (PMID 38786744, 2024). "This should assist greatly in the prevention of hypoglycaemia and hyperglycaemia at different times, the reduction and stabilisation of the insulin dosage taken, and the stabilisation of blood glucose levels." (PMID 38474713, 2024). "These issues are thought to arise from hypokalemia’s detrimental impact on pancreatic β-cell responsiveness to hyperglycemia and its interference with insulin secretion." (PMID 39055258, 2024). "Hyperglycemia induces inflammation on a cellular level, and endogenous or exogenous insulin normalizes glycemia and is also anti-inflammatory." (PMID 39176316, 2024). "Hyperglycemia, impaired insulin signaling, neuroinflammation, and oxidative stress appear to be the underlying mechanisms." (PMID 38279738, 2024).
Hyperglycemia (continued). "Insulin is produced by the β-cells of the islets of Langerhans in the pancreas and is mainly released in response to hyperglycemia." (PMID 38785837, 2024). "DM is a metabolic disorder with multiple aetiologies, characterised by chronic hyperglycaemia with disturbances in carbohydrate, fat and protein metabolism due to defects in insulin secretion, insulin action or both." (PMID 38881209, 2024). "Research has indicated that the BMT exhibits significant efficacy in enhancing insulin sensitivity, regulating insulin levels, and managing hyperglycemia." (PMID 39014283, 2024). "This ultimately culminates in an inability of the β-cells to produce sufficient insulin to overcome the lowered sensitivity, thus resulting in fasting hyperglycemia, which is clinically categorized as T2D." (PMID 38398503, 2024). "In the initial phase, intravenous insulin therapy is recommended, with a transition to subcutaneous insulin therapy when the hyperglycemia is corrected and the patient is able to tolerate oral feeding." (PMID 38594758, 2024). "In this sense, preclinical studies suggested that insulin resistance and hyperglycaemia induce the bile acids production, triggering an alteration in the bile acids homeostasis." (PMID 38743756, 2024). "Chronic inflammation of the brain also leads to an overactivation of the sympathetic nervous system, which is largely associated with increased hepatic gluconeogenesis, further contributing to hyperglycemia and insulin release." (PMID 38398503, 2024). "The choice of glucose-lowering treatment is today focused on cardiovascular and renal protection, but uncontrolled hyperglycemia often requires a targeted approach to prevent adverse outcomes, often including insulin treatment." (PMID 38441838, 2024). "In T2DM, several environmental and genetic factors contribute to impaired insulin production by pancreatic β-cells and impaired insulin sensitivity in tissues with consequent clinical manifestation of hyperglycemia." (PMID 38338796, 2024). "SGLT2 inhibitors promote urinary glucose excretion by inhibiting renal tubular SGLT2 and improve hyperglycemia in an insulin-independent manner." (PMID 38331780, 2024). "Although the insulin-lowering effect diminished with continued montelukast use, the patient reported reduced postprandial hyperglycemia." (PMID 39749265, 2024). "Individuals with T2DM typically exhibit insulin resistance and gradual β-cell deterioration, resulting in insufficient insulin secretion, and consequent hyperglycemia and elevated free fatty acid levels." (PMID 38681772, 2024). "Hyperglycemia in DM is a consequence of defects in insulin secretion, tissue resistance to insulin or a combination of both these factors." (PMID 39062768, 2024). "In diabetic rats, these NPs effectively reduced hyperglycemia, improved pancreatic insulin content and glucose tolerance, and notably increased β-cell mass." (PMID 39057094, 2024). "IR reduces cellular insulin sensitivity and attenuates physiological insulin action, which leads to hyperglycemia." (PMID 39545717, 2024). "Ad-PANX1 injection inhibited hepatic glucose production, improved glucose intolerance, decreased fasting hyperglycemia (P < 0.05), and enhanced global insulin sensitivity in mice." (PMID 38937853, 2024). "In the context of biological insulin feedback derived from hyperglycemia, liver glycogen synthesis increases through elevated phosphorylation of GSK3β, contributing to the recovery of normal glycemic homeostasis." (PMID 38755637, 2024). "While the patient was initially noted to have hyperglycemia during his hospital stay, requiring a regular insulin drip, he subsequently developed hypoglycemia even after cessation of insulin therapy." (PMID 39347250, 2024). "Low intracellular levels negatively affect tyrosine kinase activity, glucose transport in cells, and post-receptor insulin action, which, in turn, accentuates hyperglycemia." (PMID 38792906, 2024).
Hyperglycemia (continued). "Her treatment plan includes both long- and short-acting insulin, though she frequently encountered hypoglycemia and hyperglycemia." (PMID 38524636, 2024). "In the first days of life, he presented hyperglycaemia and started an intravenous insulin infusion therapy, replaced by a continuous subcutaneous insulin infusion (CSII) with Medtronic Minimed 780G® insulin pump (Medtronic, Northridge, CA, USA)." (PMID 39457190, 2024). "The main action of basal insulin is to reduce excessive hepatic glucose production and decrease overnight and between-meal hyperglycemia." (PMID 38559691, 2024). "Recently, advanced hybrid closed-loop systems have been introduced, with the development of more sophisticated algorithms that deliver and modulate basal insulin and allow automatic corrective boluses to be delivered in case of hyperglycemia." (PMID 39065641, 2024). "Persistent hyperglycemia leads to the formation of advanced glycation end-products, which further disrupt insulin signaling pathways." (PMID 39483560, 2024). "Firstly, it enables the monitoring of glycemic control, facilitating adjustments in insulin dosage to prevent hypo- and hyperglycemia." (PMID 38379866, 2024). "Muscle, liver, and adipose cells become less responsive to insulin, leading to elevated blood glucose levels, while the liver continues to produce excessive glucose, further exacerbating hyperglycemia." (PMID 39599721, 2024). "In particular, evidence has shown that hyperglycemia and insulin resistance disturb the gut‒liver axis and are closely associated with the progression of liver disease." (PMID 39570868, 2024). "This is likely due to the hyperglycaemia observed in the present study as plasma insulin concentrations appeared to be similar to previous EHC-derived values, at least during the time interval between 45 min and 75 min after the meal ingestion." (PMID 38662135, 2024). "In fact, following viral infection and because of the inflammatory state, some groups of patients can present hyperglycemia, insulin resistance and insulin secretory deficits from impaired β cells, either due to direct viral damage or indirect effects." (PMID 39081294, 2024). "Alterations in this function perturb glucose homeostasis - insufficient insulin secretion results in hyperglycemia while excess secretion leads to hypoglycemia." (PMID 38782979, 2024). "There is evidence from in vitro and animal studies showing that hyperglycemia has deleterious effects on insulin signaling in muscle." (PMID 38201980, 2024). "Mean daily exogenous insulin dosages required to control hyperglycemia individually were recorded and the levels of fasting and postprandial plasma C-peptide (PCP), as well as, HbA1c over a 4 years follow-up period were determined longitudinally." (PMID 39468609, 2024). "On the other hand, neuronal damage brought on by hyperglycemia injury is irreversible since insulin support is diminished." (PMID 39061964, 2024). "The actions of the ELo in reducing hyperglycemia and maintaining insulin levels close to those of normoglycemic animals and the glibenclamide group within 28 days suggest activation of β‐cells in the pancreas of hyperglycemic rats." (PMID 39055210, 2024). "Higher glucose and proinsulin concentrations and insulin:C-peptide ratio at T1, as well as lower QUICKI value, were significantly associated with more days with hyperglycaemia >10 mmol/L during the rest of the admission period (after T1)." (PMID 38341196, 2024). "A defect in this gene will result in insulin requiring hyperglycemia secondary to exocrine pancreatic insufficiency." (PMID 39421339, 2024). "At the same time, intensive insulin therapy for hyperglycemia also faces a lot of opposition, and the high incidence of hypoglycemia is a negative factor." (PMID 39009963, 2024). "In pregnant women with GDM, pre-pregnancy reduced insulin sensitivity and β-cell dysfunction lead to hyperglycemia." (PMID 38750456, 2024).
Hyperglycemia (continued). "Glucose metabolism was significantly altered in HFD-fed B6 mice, characterised by hyperglycaemia after glucose challenge and decreased insulin sensitivity." (PMID 39536822, 2024). "The subcutaneous administration of liraglutide not only improves hyperglycemia and peripheral IR but also reverses insulin signaling impairment in the brain, leading to decreased AD-associated tau hyperphosphorylation." (PMID 39501255, 2024). "Lipid and amino acid intakes largely impact insulin sensitivity, which is in turn a major determinant of hypo and hyperglycemia in the first days of birth of preterm infants, explaining this apparent contradiction." (PMID 38637447, 2024). "The early onset of T1D, often during adolescence, results in the need for life-long insulin therapy and intensive blood glucose monitoring to prevent both hyperglycemia and hypoglycemic episodes, which can severely impact the quality of life of patients." (PMID 38650946, 2024). "The results of β-cells destruction are insufficient insulin, hyperglycemia, polydipsia, and polyuria, which are all signs of human T1DM." (PMID 38227584, 2024). "In DM, long-term hyperglycemia results from anomalies in insulin secretion, insulin action, or both, manifesting as chronic and heterogeneous carbohydrate, lipid, and protein metabolic dysfunctions." (PMID 39334688, 2024). "In Wistar rats, 10 weeks of PHG treatment did not prevent HFD-induced weight gain but significantly mitigated fasting hyperglycemia, impaired insulin responses, and liver steatosis." (PMID 39408621, 2024). "Anti-GCGR treatment effectively reverses hyperglycemia, elevates plasma insulin levels, and restores β-cell mass through both β-cell proliferation and α-to-β-cell transdifferentiation." (PMID 39057094, 2024). "Conversely, insulin treatment effectively alleviated hyperglycemia, leading to a substantial improvement in survival rates." (PMID 38773966, 2024). "Insulin pump therapy can control hyperglycemia and reduce glycemic variability, as well as improve the quality of life more effectively in both type 1 and type 2 diabetic patients than multiple daily insulin injections." (PMID 38599884, 2024). "This increased postprandial insulin secretion is attributed to elevated β-cell sensitivity during hyperglycemia, while concurrently blunted insulin suppression is witnessed when glucose falls below fasting levels." (PMID 39200136, 2024). "Low grade inflammation in the pancreatic tissues stimulates insulin resistance, hyperglycemia and immune responses, leading to proinflammatory cytokine surge." (PMID 39070783, 2024). "IR impairs the ability of muscle, fat, and liver cells to absorb glucose from the bloodstream in response to insulin, resulting in elevated blood glucose levels (hyperglycemia)." (PMID 39337550, 2024). "Impairment of the β-cell functions results in underproduction of insulin, disturbed glucose-stimulated insulin secretion, fasting hyperglycaemia, and eventually leads to the development of T2D." (PMID 38702370, 2024). "At birth, the β-cell mass of a GK rat is already severely reduced compared to that of a Wistar rat, and in adult GK rats, the β-cell mass is usually reduced up to 60% with markedly decreased insulin secretion, which explains the early hyperglycemia." (PMID 39596183, 2024). "One participant mentioned her continued hyperglycemia was reminding her that she would need to start insulin (CGM04)." (PMID 38974988, 2024). "For steroid-induced hyperglycemia in meningioma surgery, insulin remains the treatment of choice, especially when glucose exceeds 200 mg/dL." (PMID 38715788, 2024). "Perhaps one of the greatest limiting factors to therapeutic interventions of the PAM pathway is where PAM inhibitors, alone or in combination with other therapies, induce hyperglycemia and significant increases in insulin secretion." (PMID 39456616, 2024).